EPCAM (epithelial cell adhesion molecule)
Diseases named in the same sentence as EPCAM in open-access papers (continued):
Sharing a sentence is not in itself a finding about the gene and the disease.
tumor (continued). "We thus established a multi-color immunofluorescence panel to detect CD3+CD8+Vα7.2+CD161+ putative MAIT cells in frozen tissue sections and combined these markers with EpCAM to identify the tumor cells." (PMID 31073372, 2019). "We confirmed the phenotype of HCB-514 by verifying its’ epithelial and tumor origin through cytokeratins, EpCAM and p16 staining." (PMID 30760827, 2019). "The CellSearch® system which is still considered the gold standard for the enumeration of circulating tumor cells (CTC) utilizes antibodies against the epithelial cell adhesion molecule (EpCAM) for CTC enrichment." (PMID 31636732, 2019). "Conventional CTCs detection technologies mainly rely on EpCAM-dependent capture, tumor cell size-based filtration for isolation, and immunostaining of intracellular CKs for identification." (PMID 31646374, 2019). "It is easy and simple way to estimate the tumor cell population in PDCs by analyzing EpCAM and vimentin immunofluorescence intensity." (PMID 31850215, 2019). "We performed qRT-PCR, intracellular Ca2+ monitoring, protein analyses, and real-time cell proliferation assays on EpCAM(+)CD133(+) subpopulation of tumor-initiating Huh-7 HCC cells expressing high levels of STIM1 and/or Orai1." (PMID 31366337, 2019). "Percentages of tumor cells (EpCAM+CD45-) in patients-derived spheroids and percentages of NK cells (CD3e-CD56+) and T cells (overall CD3+, CD4 T cells CD3+CD4+CD8-, CD8 T cells CD3+CD4-CD8+) in respective autologous TILs used for cocultures." (PMID 30871626, 2019). "We also analyzed additional cell populations for PD-L1 including monocytes, fibroblasts, blood endothelial cells (BECs), and EpCAM+ tumor cells based on described markers." (PMID 31244852, 2019). "Tumors characterized by VVlow expressed the epithelial cell adhesion molecule, EpCAM, less frequently (p = 0.016) and revealed a borderline correlation to increased levels of tumor cell invasion marker Loxl-2 (p = 0.059)." (PMID 31547460, 2019). "The CD3xEpCAM bispecific antibody was shown to be capable of directly stimulating CD8 T cells in vitro and reducing tumor growth in B16/EpCAM tumor-bearing mice." (PMID 31825302, 2019). "In order to demonstrate the feasibility of AvIR based PIT, we first tested CHO cells stably expressing human CEA or EpCAM as a model of target tumor cells." (PMID 31787847, 2019). "During thisprocess, tumor cells partially or completely lose theirepithelial characteristics (EpCAM and CK) and acquiremesenchymal phenotypes (vimentin), which increasetumor cell plasticity, so as to easily escape from the primarytumor into blood." (PMID 30930631, 2019). "In the spheroid culture of tumor cells, the expressionof CK and EpCAM in the presence of interferon alfaincreased by 33% and 34%, respectively, compared withthe control." (PMID 30930631, 2019). "The most common approach for separating CTCs, which has shown prognostic value in some cancer types, is by using an antibody that targets the tumor cell specific surface antigens, such as epithelial cell adhesion molecule (EpCAM)." (PMID 30744156, 2019). "Under 3D culture, tumor sphere cells formed acinar-like colonies containing both epithelial (EPCAM positive cells) and myoepithelial cells (TP63 positive cells)." (PMID 31196164, 2019). "EV EpCAM signal was observed to significantly increase (p-value <0.005 for all mice) by two weeks after transplant and subsequent EV EpCAM signal was observed to correlate (R2 > 0.99 for all mice) with changes in the xenograft tumor volume." (PMID 31921310, 2019). "We next evaluated the correlation between the lymphocytes per ml of each subpopulation and the number of EpCAM+ CD45− tumor cells per ml." (PMID 30816121, 2019). "Detection of EpCAM-positive CTCs by the FDA cleared CellSearch System has already been shown to have a prognostic impact in many tumor entities." (PMID 31481116, 2019). "This EpApt nanocomplex was able to target EpCAM tumor cells, deliver the siRNA, and silence the target gene." (PMID 31861277, 2019).
tumor (continued). "CUR nanoparticles were functionalized with aptamers (Apt) that bind specifically to epithelial cell adhesion molecule (EpCAM) found on tumor surfaces." (PMID 30890933, 2019). "In the peripheral blood of patients with HCC, the EpCAM-based identification of circulating tumor cells (CTCs) is considered to be an indicator of portal vein thrombosis, early recurrence risk, and high metastatic potential." (PMID 31781608, 2019). "IFNα-2b inhibited migration of tumor cells to the suspension fraction and promoted an increase in expression of CK and EpCAM in 2D and 3D cell cultures, but only in the 3D culture was expression of vimentin increased." (PMID 30930631, 2019). "Inthe 2D culture, tumor cell culture of IFNα-2b promotedincreased expression of CK and EpCAM by 50.5% and47.8%, respectively, as compared to the control." (PMID 30930631, 2019). "Epithelial cell adhesion molecule (EpCAM) is an epithelial cell-specific surface marker widely expressed on both normal and tumor epithelium." (PMID 31141571, 2019). "Before proceeding with patient sample analysis, a series of spiking experiments using cells from tumor cell lines with different EpCAM densities was performed in order to validate the test." (PMID 31636732, 2019). "To concentrate live tumor-infiltrating immune cells, we considered the removal of dead cells and/or epithelial tumor cells by magnetic separation on autoMACS after labeling of annexin V or EpCAM, respectively." (PMID 30886872, 2019). "EpCAM expression in tumor tissues is significantly higher than that in para-cancerous tissues, which is in accord with former publications." (PMID 31354723, 2019). "Current systems of isolation rely on methods based on physical differences between hematopoietic cells and tumor cells and on immune cytokeratin expression such as the epithelial cell adhesion molecule (EpCAM)." (PMID 30736478, 2019). "A clinicopathological analysis showed that EpCAM expression is significantly higher in tumor tissues from patients who received platinum-based chemotherapy than in corresponding tumor tissues before chemotherapy." (PMID 31261739, 2019). "Using the differential intensity levels of EpCAM and vimentin, we formulated an image-based tumor purity estimation to measure the tumor cell index." (PMID 31850215, 2019). "Treatment with the CD3xEpCAM bispecific antibody significantly reduced the growth of tumors and extended survival of B16F10/EpCAM tumor-bearing mice compared with CD3xnull-treated animals." (PMID 31825302, 2019). "This molecule was engineered to harbor a mouse IgG2aσ silent Fc, with one variable region arm specific for mouse CD3ɛ and the other arm specific for human EpCAM to permit targeting of murine tumor cells expressing human EpCAM." (PMID 31825302, 2019). "Here, we will review the accumulating recent evidence that EpCAM is a special tumor marker with profound biological properties far beyond inter-cellular adhesion." (PMID 31225512, 2019). "In this system, the magnetic nanospheres (120–200 nm) were modified with anti-EpCAM antibody and biotin analogue, and then, the functionalized magnetic nanospheres were used to capture tumor cells." (PMID 34138055, 2019). "A key finding from their IMC analysis was the lower expression of EpCAM on tumor cells in the bone marrow compared to the prostate." (PMID 31798587, 2019). "Liver stem-like cells within tumors (i.e., tumor-initiating cells (T-ICs)) are characterized by several cell marker molecules, such as EpCAM and CD133." (PMID 30718464, 2019). "The role of EpCam (CD326) in tumor biology and metastasis is less clear, and reports find both anti-metastatic as well as pro-metastatic activity of CD326, depending on the microenvironment and tumor model." (PMID 31450811, 2019).
tumor (continued). "These tumors are heterogeneous and contain not only cancer cells expressing EpCAM, but also mesenchymal cells, fibroblasts, glandular cells, immune and other blood cells, epithelial cells, necrotic cells, tumor stroma, etc." (PMID 30871104, 2019). "EpCAM, a 40-kDa transmembrane glycoprotein, is a promising therapeutic target for antitumor schemes for its tumor-specific overexpression." (PMID 31354723, 2019). "A significant increment in tumor cell death was confirmed also in immunofluorescence experiments where EpCAM positive cells become propidium positive when treated with scDb." (PMID 31708930, 2019). "The three most commonly employed biomarkers utilized for tumor cell selection and identification are the epithelial-cell-adhesion-molecule (EpCAM), cytokeratins, and the antigen CD45." (PMID 31174404, 2019). "A third strategy tries to overcome this limitation by enriching circulating/disseminated tumor cells, for example by selecting for the epithelial marker EpCAM." (PMID 29721166, 2018). "The detected tumor markers mainly included epithelial cell adhesion molecule (EpCAM), cytokeratin, and epidermal growth factor receptor (EGFR)." (PMID 30192876, 2018). "In vivo efficacy was demonstrated using an EpCAM-positive human tumor xenograft model in severe combined immunodeficiency (SCID) mice; the majority of treated mice being tumor free at the end of the study." (PMID 30096764, 2018). "The presence of high expressing epithelial cell adhesion molecule (EpCAMhigh) circulating tumor cells (CTC) enumerated by CellSearch® in blood of cancer patients is strongly associated with poor prognosis." (PMID 30479699, 2018). "The xenografts contain approximately 75% human tumor cells, based on cell surface expression of CD326 (human EpCAM)." (PMID 29510720, 2018). "As we all know, during the EMT process of tumor cells, the expression of epithelial cell adhesion molecule (EpCAM) and cytokeratins (CK) will be downregulated, while the expression of twist and vimentin will be upregulated." (PMID 30046606, 2018). "As an oncogene, EpCAM promotes carcinogenesis, cell proliferation and survival, resulting in accelerated tumour growth and metastasis." (PMID 30419852, 2018). "In contrast, exosomes obtained on day 7 or 4-6 weeks after PDT carried E-cadherin, restored epithelial morphology and EpCAM expression in tumor cells, down-regulated expression of mesenchymal genes and inhibited proliferation, migration and invasion." (PMID 29854876, 2018). "Previous clinical studies have also reported an association between the expression of particular HPC markers and tumour malignant behaviour which is consistent with our data on EpCAM." (PMID 29774107, 2018). "Expression of classic tumor-associated proteins such as β-catenin, EpCAM and CK19 was maintained in acini-like organized tumors on CAM, as was synthesis of AFP, a tumor marker used for monitoring patient response." (PMID 29662633, 2018). "Nonetheless, EpCAM and Sox2 possessed prognostic value, even under these testing conditions and in the presence of the primary tumor throughout the observation period (Göttingen cohort)." (PMID 30275505, 2018). "EpCAM-specific CAR T cells exhibited substantial anti-tumor toxicity against prostate metastatic tumor cells." (PMID 30108584, 2018). "Dynamic changes in EpCAM expression frequently occur during tumor progression and its downregulation was observed during EMT." (PMID 30200242, 2018). "EPCAM is highly expressed in carcinomas, tumor-initiating cells, tissue progenitor cells, embryonic, and adult stem cells, but at lower levels in normal epithelia." (PMID 29498629, 2018). "For example, if EpCAM expression is considered for breast cancer, an over-expression suggests poorer prognosis, greater tumour size, lymph node involvement, tumour stage, and tumour grade." (PMID 29329202, 2018).
tumor (continued). "In this paper, we evaluated the use of EpCAM, E-cadherin, and cytokeratins for detection of metastasis in tumor draining lymph nodes from penile cancer patients by flow cytometry." (PMID 30290760, 2018). "We found that KD of EpCAM significantly inhibited tumour growth, increased xenograft sensitivity to chemotherapy/radiotherapy, and prolonged the survival of tumour-bearing mice." (PMID 30419852, 2018). "To confirm the characterization of CAFs, we assessed several markers, including α-SMA and EpCAM, that are used to distinguish fibroblasts from tumor cells." (PMID 29988148, 2018). "In this study, the ratio of podoplanin-positive/EpCAM-positive CTCs showed an independent prognostic value with respect to the type of treatment and tumour staging." (PMID 29890622, 2018). "The effect of EpCAM-knockdown (KD) on tumour growth, chemo−/radiotherapy response and animal survival was evaluated on subcutaneous (s.c) and orthotopic mouse models." (PMID 30419852, 2018). "EpCAM+ prostate CSCs can be an appropriate target for EpCAM-specific CAR T cells since they have an important role in tumor proliferation and progression." (PMID 30108584, 2018). "We found that CTA treatment not only led to increased EpCAM expression at early stages, but also to a selection of more aggressive tumor cells with a continued increased EpCAM expression, even post-treatment." (PMID 30116994, 2018). "Transgenic mice with miRNA122a knockout have been shown to spontaneously develop HCC with the miRNA122a −/− tumor cells showing increased expression of CSC markers such as EpCAM, CD90 and CD133." (PMID 29805757, 2018). "The results showed that vaccination of nude mice with EpCAM peptide-CTLs delayed tumor growth induced by HepG2 cells." (PMID 29298343, 2018). "These molecular networks with reported functionality in tumor progression and treatment resistance prompted us to investigate protein co-expression levels and patterns of Sox2, EpCAM and vimentin in HNSCC." (PMID 30275505, 2018). "At the moment, our results strongly indicate that EpCAM expression in HCCs is an indicator of increased tumour malignancy and poor prognosis." (PMID 29774107, 2018). "Tumor-specific CTLs against EpCAM+ HepG2 cells were evaluated with by FACS analysis using lymphocytes from the four treated groups." (PMID 29298343, 2018). "Concerning EpCAM, it was shown that EpCAM and transcription factors Oct4, Nanog, Sox2 and c-Myc are concomitantly expressed in colon TICs and EpCAM overexpression enhanced tumor sphere formation." (PMID 29652830, 2018). "During EMT, the morphology of the tumor cells dramatically changes, so cells gain invasive capabilities and migratory functions, and epithelial cell adhesion molecule (EpCAM) expression is decreased." (PMID 29734758, 2018). "Human-specific EpCAM and pan-cytokeratin, which are commonly used to detect tumor cells, were also tested but resulted in background staining of mouse bone marrow (data not shown)." (PMID 30250146, 2018). "A recent paper by Xiang and colleagues tested the ability of an EpCAM antibody to penetrate and be retained in vivo into a xenograft tumour." (PMID 29329202, 2018). "While most carcinomas are considered EpCAM positive, the expression of EpCAM is often heterogenous within the tumor." (PMID 30115931, 2018). "EpCAM has key signaling functions during embryonic development and is expressed at high levels in epithelial derived cancers and circulating tumor cells." (PMID 30304739, 2018). "Here, we analyzed scFv-Fc-scTRAIL molecules directed against EGFR, HER2, HER3, and EpCAM as well as an untargeted Fc-scTRAIL fusion protein for their potentials to induce cell death both in vitro and in a xenograft tumor model in vivo." (PMID 29541416, 2018). "Numerous studies have indicated that various surface markers such as CD133, CD90, ALDH, and EpCAM, are used to identify and isolate CSCs in cancer types, and that their expression levels are different from those of other bulk tumor cells." (PMID 28290053, 2018).
tumor (continued). "We analyzed the fraction of cells with EpCAM and CD146 co-expression (EpCAM+/CD146+) along with tumor tissue grading." (PMID 30185225, 2018). "The tumor tissue from the EpCAM peptide-CTLs group showed weak expression, as determined by EpCAM immunohistochemical staining." (PMID 29298343, 2018). "Because EpCAM is expressed exclusively in epithelia and epithelial-derived neoplasms, anti-EpCAM antibody is widely applied to immune-based capture of cancer cells in blood so far." (PMID 30104638, 2018). "Flow cytometric profiling revealed heterogeneous mHsp70 and EpCAM expression patterns in cancer cell lines, and it is expected that the level of heterogeneity within and between different tumor entities will be even more marked in the clinical setting." (PMID 30443493, 2018). "Many of the techniques for isolating CTCs are based on the expression of epithelial cell surface adhesion molecule (EpCAM, CD326) on tumor cells." (PMID 30443493, 2018). "Here, we provide molecular evidence that EPCAM-positive cells isolated via IE/FACS from the bone marrow display molecular features that are consistent with a tumor phenotype." (PMID 30211312, 2018). "Having learnt from these experiences, the next antibody generated, Adecatumumab, had a moderate affinity for EpCAM, and spared the normal cells while targeting the tumour cells." (PMID 29329202, 2018). "The GILUPI CellCollector® directly captures tumor cells from the patient's blood stream using an EpCAM antibody-coated CellCollector® system inserted into the cubital veins over a 30 min period." (PMID 30443493, 2018). "It was found that KD of EpCAM can significantly reduce tumour growth in both s.c. and orthotopic mouse models, respectively." (PMID 30419852, 2018). "The knockdown of EpCAM inhibited several tumor properties and decreased the expression of EMT genes." (PMID 29652830, 2018). "An anti-EpCAM ADC conjugated with α-Amanitin payload via a protease/esterase sensitive glutamate linker was also found to be highly effective in EpCAM expressing tumor models." (PMID 29642542, 2018). "The FACS-based cytotoxicity assay of tumor-specific CTLs against EpCAM+ HepG2 cells using lymphocytes from the four treatment groups showed that EpCAM peptide-CTLs increased the cytotoxic activity significantly as the ratio of effectors to targets increased." (PMID 29298343, 2018). "To examine the effects of Pep-CTLs on EpCAM expression in tumor tissue, we performed immunohistochemical analyses." (PMID 29298343, 2018). "Based on the analysis of our experimental data, this study presents the first evidence that BCYRN1 is upregulated in GC and acts as an oncogene to promote tumor progression and increase EpCAM expression." (PMID 29435146, 2018). "In this study, Kaplan-Meier analysis was used to assess the relationship between expression of EpCAM and survival outcomes of CaP tumour-bearing mice." (PMID 30419852, 2018). "In order to address the impact of EGFR and EpCAM expression on tumor cell behavior at the mechanistic level, we established an in vitro mimic of the clinical situation." (PMID 30261040, 2018). "The growth suppression efficacy of combination therapy with regorafenib and CAR-NK-92 cells on established EpCAM-positive tumor xenografts was more significant than that of monotherapy with CAR-NK-92 cells or regorafenib." (PMID 30410941, 2018). "Different subsets of circulating tumor cells were determined on the basis of the expression of EpCAM, CD45, CD44, CD24, and N-Cadherin using flow cytometry." (PMID 29565320, 2018). "A typical approach to capture and identify CTCs is by utilizing the tumor-specific antibodies as reflected by the epithelial cell adhesion molecule (EpCAM)." (PMID 30424040, 2018). "In in vitro and in vivo experiments, it suppressed EpCAM expression, reduced the proportion of EpCAM+ tumor cell,s and inhibited tumor formation." (PMID 30112355, 2018).